AQP4 (aquaporin 4)
Diseases named in the same sentence as AQP4 in open-access papers (continued):
Sharing a sentence is not in itself a finding about the gene and the disease.
neuromyelitis optica spectrum disorder (continued). "Recent data further suggested that GLT-1 and AQP4 exist in astrocytic membranes as a macromolecular complex, as neuromyelitis optica-immunoglobulin G autoantibodies directed against AQP4 result in the concomitant loss of GLT-1." (PMID 27057365, 2016). "AQP4 has also been described as an autoantigen in neuromyelitis optica (NMO), an inflammatory disease of the central nervous system, mainly affecting the spinal cord and the optic nerve." (PMID 25986484, 2015). "AQP4-IgG has recently been identified as a marker for Neuromyelitis optica, a disorder with demyelination of optic nerve and cervical spinal cord." (PMID 25986484, 2015). "In our study, 4 patients developed partial myelitis and anti-AQP4 Ab seronegativity, and these findings are inconsistent with the presence of a benign form of neuromyelitis optica." (PMID 26485719, 2015). "Reversible leukoencephalopathy has been described in few anti-aquaporin-4 antibody positive neuromyelitis optica (NMO) cases following immunotherapeutic interventions." (PMID 26329680, 2015). "Neuromyelitis optica is characterised by optic neuritis, longitudinally-extensive transverse myelitis and presence of anti-aquaporin-4 antibodies in the serum." (PMID 25888897, 2015). "We report 2 patients to illustrate the varied clinical manifestations of neuromyelitis optica spectrum disorders while postulating an effect of anti-aquaporin-4 antibodies on the miscarriage of pregnancy." (PMID 25888897, 2015). "Aquaporin-4 antibody (AQP4-Ab)-positive neuromyelitis optica spectrum disorder (NMOSD) is a rare but often severe autoimmune disease with median onset around 40 years of age." (PMID 25957640, 2015). "Neuromyelitis optica-immunoglobulin G (NMO-IgG) binds to aquaporin-4 (AQP4) water channels in the central nervous system leading to immune-mediated injury." (PMID 25792738, 2015). "Increasing rates of AQP4-seropositive neuromyelitis optica spectrum disorder (NMOSD) have been reported in late-onset patients (LONMOSD)." (PMID 26337073, 2015). "In neuromyelitis optica (NMO), astrocytes become targets for pathogenic aquaporin 4 (AQP4)-specific antibodies which gain access to the central nervous system (CNS) in the course of inflammatory processes." (PMID 26530185, 2015). "Our report highlights the varied central nervous system manifestations of neuromyelitis optica spectrum disorders and miscarriage of pregnancy possibly related to anti-aquaporin-4 antibodies." (PMID 25888897, 2015). "Neuromyelitis optica (NMO), an autoimmune astrocytopathic disease associated with anti-aquaporin-4 (AQP4) antibody, is characterized by extensive necrotic lesions preferentially involving the optic nerves and spinal cord." (PMID 26637322, 2015). "In a mouse model of neuromyelitis optica induced by anti-aquaporin-4 antibodies, IdeS treatment greatly reduced pathological lesions." (PMID 26194472, 2015). "The critical role of AQP4 in astrocyte functions is evenly evident in pathological conditions, including cerebral edema, intracerebral hemorrhage, neuromyelitis optica, neuroinflammation, and epilepsy." (PMID 26526066, 2015). "The seropositivity for aquaporin-4 antibodies is used for the diagnosis of neuromyelitis optica or neuromyelitis optica spectrum disease." (PMID 27379319, 2014). "Its physiopathology is connected with the aquaporin-4 water channel, since antibodies against aquaporin-4 have been found in the cerebrospinal fluid and blood of neuromyelitis optica patients." (PMID 27379319, 2014). "The discovery of the anti-aquaporin-4 (AQP4) antibody advanced our understanding of neuromyelitis optica (NMO)." (PMID 25259647, 2014). "Spinal imaging and anti-aquaporin-4 antibody positivity established a diagnosis of neuromyelitis optica spectrum disorder." (PMID 25169022, 2014). "Here, we describe a 67-year-old Caucasian man with definite neuromyelitis optica with detection of anti-aquaporin-4 antibodies over the course of the disease." (PMID 24886528, 2014).
neuromyelitis optica spectrum disorder (continued). "Neuromyelitis optica spectrum disorders (NMOSD) is a group of inflammatory demyelinating disorders, mediated by pathogenic autoantibodies (NMO-IgG) against astrocyte aquaporin-4 (AQP4), the main water channel of the central nervous system (CNS)." (PMID 25526927, 2014). "We microinjected MOG-IgG, obtained from patients with neuromyelitis optica, into mouse brains and compared the results with AQP4-IgG." (PMID 24685353, 2014). "Neuromyelitis optica (NMO) is an autoimmune inflammatory condition of the central nervous system that is characterized by circulating anti-aquaporin-4 antibodies, transverse myelitis and optic neuritis." (PMID 25169022, 2014). "Neuromyelitis optica (NMO) or Devic's disease is an autoimmune disorder affecting the optic nerve and spinal cord, where the aquaporin-4 water channel (AQP4) plays an important role." (PMID 27379319, 2014). "Both patients were later diagnosed with neuromyelitis optica spectrum disorders (NMOSD) supported by their AQP4-seropositivity." (PMID 24029914, 2014). "Devic's disease is differentiated from RRMS by the presence of aquaporin-4 antibodies and rare involvement of the cerebrum in Devic's disease." (PMID 27355035, 2014). "Antibodies against myelin oligodendrocyte glycoprotein (MOG-IgG) are present in some neuromyelitis optica patients who lack antibodies against aquaporin-4 (AQP4-IgG)." (PMID 24685353, 2014). "Autoantibodies against aquaporin-4 (AQP4), a water channel in CNS astrocytes, are detected in ∼50–80% of patients with neuromyelitis optica spectrum disorders (NMOsd), characterized by longitudinally extensive transverse myelitis (LETM) and/or optic neuritis." (PMID 24086369, 2013). "Corticosteroid therapy is a first-choice treatment for anti-aquaporin 4 antibody-positive neuromyelitis optica." (PMID 23575376, 2013). "A primary role for AQP4 has been associated with neuromyelitis optica (NMO), an autoimmune inflammatory astrocytopathy caused by complement-activating IgG autoantibodies directed against AQP4." (PMID 24252214, 2013). "Cell-based assays (CBA) have increased the sensitivity of the neuromyelitis optica (NMO)-IgG/aquaporin-4-antibody detection compared to classical tissue-based indirect assays." (PMID 24223884, 2013). "Neuromyelitis optica (NMO) is an autoimmune disease targeting aquaporin 4 (AQP4), localized mainly at the astrocytic foot processes." (PMID 23579868, 2013). "In this report, we describe a case of successful trabeculotomy performed on a patient with corticosteroid-induced glaucoma and anti-aquaporin 4 antibody-positive neuromyelitis optica." (PMID 23575376, 2013). "Recent advances in the field of neuromyelitis optica (NMO) research provided convincing evidence that anti-AQP4 antibody (AQP4-Ab) not only serves as a highly specific disease marker, but also plays an essential role in the pathogenesis of the disease." (PMID 22530129, 2012). "HAM/TSP can present with an acute/subacute form of longitudinally extensive myelitis, which can be confused with lesions seen in aquaporin-4 antibody (AQP4-Ab) positive neuromyelitis optica spectrum disorders (NMOSD) on MRI." (PMID 22808032, 2012). "The diagnostic and pathophysiological relevance of antibodies to aquaporin-4 (AQP4-Ab) in patients with neuromyelitis optica spectrum disorders (NMOSD) has been intensively studied." (PMID 22260418, 2012). "The possible link between neuroinflammation and AQP4 was advertised with neuromyelitis optica (NMO), a demyelinating disease." (PMID 23270503, 2012). "The clinical spectrum of autoimmune ON includes Neuromyelitis Optica (NMO, Devic disease) and disease occurring as part of an Aquaporin 4 antibody spectrum (AQP4+), as well as Chronic Relapsing Inflammatory Optic Neuropathy (CRION)." (PMID 23316360, 2012).
neuromyelitis optica spectrum disorder (continued). "We believe that the identification of the AQP4 determinants that evoke I-Ab restricted T cell responses is a further step towards the development of an animal model for Devic's disease that would incorporate both T cell and B cell mediated anti-AQP4 responses." (PMID 21264240, 2011). "Autoantibodies that target the water channel aquaporin-4 (AQP4) in neuromyelitis optica (NMO) are IgG1, a T cell-dependent Ig subclass." (PMID 21151500, 2010). "The involvement of astrocyte water channel aquaporin-4 (AQP4) in autoimmune diseases of the central nervous system has been suggested following the identification of AQP4 autoantibodies in neuromyelitis optica, an inflammatory demyelinating disease." (PMID 19660138, 2009). "Antibodies to AQP4 have ahighly specific role in neuromyelitis optica (NMO) and characteristically bindto cerebral microvessels, pia mater, and VRSs." (PMID 19229345, 2008). "However, there is a paucity of real-world data evaluating its performance in Chinese patients with aquaporin-4 immunoglobulin G–seropositive neuromyelitis optica spectrum disorder (AQP4-IgG+ NMOSD)." (PMID 41601647, 2026). "The genus Barnesiella showed protective effect on IS and small vessel stroke while posed a risk effect on neuromyelitis optica spectrum disorder (NMOSD), as well as on aquaporin-4 immunoglobulin G-positive neuromyelitis optica spectrum disorder (AQP4-IgG+ NMOSD)." (PMID 40825663, 2025). "Moreover, we compared these data with APS patients in aquaporin-4-IgG-positive neuromyelitis optica spectrum disorders (AQP4-IgG+ NMOSD)." (PMID 39949796, 2025). "This case series examines long-term outcomes for 2 aquaporin-4-IgG (AQP4-IgG)–positive patients with neuromyelitis optica spectrum disorder (NMOSD) who underwent autologous hematopoietic stem cell transplantation with a nonmyeloablative conditioning regimen and rituximab." (PMID 40257801, 2025). "Neuromyelitis optica spectrum disorder (NMOSD) is an autoimmune inflammatory disorder of the central nervous system that primarily affects young women and is associated with antibodies against aquaporin-4 (AQP4)." (PMID 40995295, 2025). "The closely similar disorder NMO (neuromyelitis optica), which was formerly included in the MS spectrum, is now recognized as a distinct entity due to the discovery that the target antigen of the antibody is the water channel anti-Aquaporin 4 (AQP4)." (PMID 40364858, 2025). "While some antibodies are helpful for differential diagnosis, such as anti-aquaporin 4 (AQP4), primarily associated with neuromyelitis optica spectrum disorders (NMOSDs), glial fibrillary acidic protein (GFAP) antibodies are typically found in patients with autoimmune GFAP astrocytopathy." (PMID 39859557, 2025). "In Neuromyelitis Optica Spectrum Disorder (NMOSD), drugs like rozanolixizumab can rapidly reduce anti-AQP4 antibody titers and decrease the risk of acute attacks, with some drugs submitted for relevant indications in Europe and the US, potentially becoming new maintenance therapy options." (PMID 41471322, 2025). "Multiple sclerosis (MS), aquaporin-4 antibody-positive neuromyelitis optica spectrum disorder (AQP4-Ab + ve NMOSD), and myelin oligodendrocyte glycoprotein-associated disease (MOGAD) are demyelinating diseases with differing pathophysiological processes and treatments." (PMID 40773034, 2025). "Aquaporin-4 antibody-positive neuromyelitis optica spectrum disorder (AQP4-NMOSD) and myelin oligodendrocyte glycoprotein antibody disease (MOGAD) are antibody-associated inflammatory diseases of the central nervous system with predominant involvement of the spinal cord and optic nerves." (PMID 40088045, 2025). "Comorbidities occur in aquaporin‐4 antibody‐positive neuromyelitis optica spectrum disorder (AQP4‐NMOSD), myelin oligodendrocyte glycoprotein antibody‐associated disease (MOGAD), and double seronegative NMOSD (DN‐NMOSD), potentially contributing to a less favorable disease course." (PMID 40485599, 2025).
neuromyelitis optica spectrum disorder (continued). "Neuromyelitis optica spectrum disorder (NMOSD), first described by Devic in 1894 and previously considered a severe variant of multiple sclerosis (MS), is now recognized as a distinct autoimmune astrocytopathy mediated by aquaporin-4 (AQP4) antibodies." (PMID 41306148, 2025). "Multiple sclerosis (MS), aquaporin-4 antibody positive neuromyelitis optica spectrum disorder (AQP4-Ab + ve NMOSD), and myelin oligodendrocyte glycoprotein antibody-associated disease (MOGAD) are three discrete autoimmune diseases of the central nervous system (CNS) that cause demyelination." (PMID 40773034, 2025). "A lumbar puncture was also performed, which showed a normal opening pressure with a negative oligoclonal IgG bands test, negative anti-myelin-associated glycoprotein antibody (MAG) test, and negative neuromyelitis optica/Aquaporin-4 (NMO) antibody test." (PMID 40821180, 2025). "Anti-aquaporin-4 antibody-positive (AQP4+) neuromyelitis optica spectrum disorder (NMOSD) is a rare, severe, disabling autoimmune inflammatory disease of the central nervous system (CNS) that predominantly affects the optic nerve, the brainstem and the spinal cord." (PMID 38356884, 2024). "The high incidence of MME in neuromyelitis optica could therefore be related to the presence of anti-AQP4 antibodies." (PMID 39311320, 2024). "Myelin oligodendrocyte glycoprotein (MOG) antibody immunoglobulin G (IgG)-associated disease (MOGAD) has clinical and pathophysiological features-like but distinct from those of aquaporin-4 antibody (AQP4-IgG)-positive neuromyelitis optica spectrum disorders (AQP4-NMOSD)." (PMID 39456143, 2024). "More recently, we have shown that IFN-γ is essential for maintaining immune tolerance to aquaporin-4 (AQP4) antigen and that its absence leads to autoimmune inflammation and severe clinical disease resembling AQP4-IgG+ neuromyelitis optica spectrum disorders (NMOSD)." (PMID 38822334, 2024). "On the other hand, experiments of passive co-transfer of in vitro polarized anti-GluN1 T helper cells with anti-GluN1 Abs would be useful to decipher the immune mechanisms in NMDAR AE as it was performed in the neuromyelitis optica rodent model with the aquaporin 4 autoantigen." (PMID 39595024, 2024). "Certain demyelinating disorders, such as neuromyelitis optica spectrum disorder (NMOSD) and myelin oligodendrocyte glycoprotein antibody-associated disease (MOGAD) exhibit serum autoantibodies against aquaporin-4 (αAQP4) and myelin oligodendrocyte glycoprotein (αMOG)." (PMID 38580905, 2024). "We also performed immunocytochemistry on the human epithelial cell line Hep-2, a test commonly employed to detect anti-nuclear antibodies in SLE and a cell line expressing AQP4, which identifies subjects that may be diagnosed with Neuromyelitis Optica." (PMID 38915059, 2024). "Satralizumab provides durable inhibition of IL-6 signaling and is indicated for another autoantibody-mediated neuroimmunological disease, aquaporin-4 immunoglobulin G antibody-positive neuromyelitis optica spectrum disorder, as monotherapy or as an add-on to immunosuppressive therapy (IST)." (PMID 39193150, 2024). "AQP4-antibody differentiates neuromyelitis optica from multiple sclerosis." (PMID 39430225, 2024). "Thus, MOGAD is generally considered to have a favorable prognosis compared to other CNS demyelinating diseases such as AQP-4 positive neuromyelitis optica spectrum disorder (NMOSD) and multiple sclerosis (MS)." (PMID 39318613, 2024). "Myelin oligodendrocyte glycoprotein antibody (MOG) immunoglobulin G (IgG)-associated disease (MOGAD) has clinical and pathophysiological features that are similar to but distinct from those of aquaporin-4 antibody (AQP4-IgG)-positive neuromyelitis optica spectrum disorders (AQP4-NMOSD)." (PMID 38576611, 2024).
neuromyelitis optica spectrum disorder (continued). "For example, neuromyelitis optica spectrum disorder (NMSOD) may involve cross-reactive epitopes between human aquaporin-4 and the Tax protein of the Human T-lymphotropic virus type 1 (HTLV-1)." (PMID 39561198, 2024). "In addition to AchR-Ab-positive gMG, eculizumab showed efficacy in paroxysmal nocturnal hemoglobinuria (PNH), atypical hemolytic uremic syndrome (aHUS), and aquaporin-4 (AQP-4)-Ab-positive neuromyelitis optica spectrum disorder (NMOSD)." (PMID 40757546, 2024). "In neuromyelitis optica cases, more deposition of C9neo (a complement attack complex), microglia activation and granular cells infiltration, and less AQP4 expression, were observed in the pia, ependyma and choroid plexus epithelium when compared to the normal and multiple sclerosis tissues." (PMID 37238624, 2023). "Relapsing-remitting multiple sclerosis (RRMS), aquaporin-4 antibody–positive neuromyelitis optica spectrum disorder (AQP4-NMOSD), and myelin oligodendrocyte glycoprotein antibody–associated disease (MOGAD) may have overlapping clinical features." (PMID 36192175, 2023). "However, in June 2020, inebilizumab received global approval in the USA for the treatment of neuromyelitis optica spectrum disorder in adult patients who are seropositive for IgG autoantibodies against aquaporin-4 (AQP4-IgG)." (PMID 37296844, 2023). "Case 4: Neuromyelitis optica with positive anti-aquaporin 4 antibody." (PMID 38005993, 2023). "Finally, it was in the 2005 McDonald criteria when aquaporin-4 (AQP4) serum antibody testing for neuromyelitis optica spectrum disorder (NMOSD) was first recommended to be performed in all cases with clinical manifestations suggestive of NMOSD." (PMID 38202221, 2023). "Phase 3 randomized controlled trial (RCT) data for Aqp-4-positive NMOSD (PREVENT, prevention of relapses in neuromyelitis optica; NCT01892345) showed a remarkable 94% relative risk reduction of relapses however the benefits were less clear in the RCT data for MG." (PMID 37869140, 2023). "The term ‘neuromyelitis optica spectrum disorders’ (NMOSD) is used as an umbrella term that refers to aquaporin-4 immunoglobulin G (AQP4-IgG)-positive neuromyelitis optica (NMO) and its formes frustes and to a number of closely related clinical syndromes without AQP4-IgG." (PMID 37022481, 2023). "However, on CBA, one case of aquaporin-4-positive neuromyelitis optica was positive (all remaining NMOSD sera and other healthy or disease-control sera and CSF were negative on CBA)." (PMID 37795104, 2023). "In addition, it is known that dysfunction of AQP4 exists, such as occurring due to the formation of autoantibodies to AQP4 in neuromyelitis optica spectrum disorder (NMOSD) with EPVS." (PMID 37374328, 2023). "White blood cell (WBC) count profiles in anti-aquaporin-4 antibody-positive neuromyelitis optica spectrum disorder (AQP4-NMOSD) and anti-myelin oligodendrocyte glycoprotein antibody-associated disease (MOGAD) are still unknown." (PMID 37081126, 2023). "Area postrema syndrome (APS), which refers to episodes of intractable nausea, vomiting or hiccups mimicking gastrointestinal disorders, is one of the six core clinical characteristics of aquaporin-4 (AQP4)-IgG seropositive neuromyelitis optica spectrum disorder (NMOSD)." (PMID 36805663, 2023). "Cumulative damage from multiple relapses in neuromyelitis optica spectrum disorder (NMOSD) is associated with poor health-related quality of life (HRQoL) and long-term disability in patients positive for anti-aquaporin 4 antibodies (AQP4+)." (PMID 37114235, 2023). "Compared to aquaporin 4 (AQP4) antibody-positive neuromyelitis optica spectrum disorders (NMOSD), perivenous complement deposition is less common, but can be seen on myelinated fibers and on myelin degradation products within macrophages, resembling MS Pattern II pathology." (PMID 37545724, 2023).